SHH (sonic hedgehog signaling molecule)
Diseases named in the same sentence as SHH in open-access papers (continued):
Sharing a sentence is not in itself a finding about the gene and the disease.
tumor (continued). "Direct comparison between KIRC tumor tissues and morphologically unchanged (control) kidney samples revealed a lack of statistical difference between the expression of SHH and approximately 1.25- and 1.5 higher immunoreactivity of GLI1 and VEGFA proteins, respectively, in cancer cells." (PMID 37964226, 2023). "Furthermore, Qingjie Fuzheng Granule (QFG) could significantly reduce the protein expression of the Sonic Hedgehog pathway-related proteins SHH, Smo and Gli1 in HCT-116 xenograft mice tumor tissues." (PMID 36782251, 2023). "Another combination of PEG-Gem-cisPt-MSNs and synthetic consisting of SHH inhibitor, cyclopamine (CyP), and mesoporous silica nanoparticles (MSN) have been corroborated in vivo evaluation to enhance the efficiency of drug delivery to tumor cells and reduce tumor mass." (PMID 37784082, 2023). "Upactivation of the HH signaling pathway in cancer cells induces GLI1 and SHH overexpression, which increases the expression of proangiogenic factors, including VEGF-A, MMP-2, MMP-9, heparanase, and cysteine-rich angiogenic inducer 61 (Cyr61), in different tumor cells." (PMID 37626893, 2023). "Vice versa, typical SHH marker genes are not expressed by tumor cells of all three MYC subtypes." (PMID 35318328, 2022). "However, the focus now has shifted towards stromal modulation rather than depletion (unlike SHH inhibitors and hyaluronidase, which can also lead to altered tumor immune microenvironments)." (PMID 35154473, 2022). "Indeed, inhibitors of the SHH pathway effector SMO have been successfully tested in both in vitro and in vivo GBM models and demonstrated to efficiently counteract self-renewal and tumor progression." (PMID 34439999, 2021). "In the tumor microenvironment, potential stimuli that activate fibroblasts include bone morphogenetic protein (BMP), interleukin-1, interleukin-6, platelet-derived growth factor (PDGF), sonic hedgehog (SHH), reactive oxygen species (ROS), transforming growth factor-β (TGF-β), as well as TNF." (PMID 33614646, 2021). "Importantly, these SHH-immunoreactive cells were not derived from the cell of origin suggesting these reactive astrocytes were recruited to the tumor to provide an SHH-rich microenvironment." (PMID 32957513, 2020). "IDHWT recurrent tumours were not mutated in NOTCH, SHH, Rb, or IDH genes." (PMID 32082376, 2019). "However, we do not mean to imply that SHH expression is a read out of Hh pathway activation or Gli signaling, except perhaps in some tumor cells with highly dysregulated signaling." (PMID 31652618, 2019). "The presence of aggresomes in ≥20% of the tumor identified poor responders in standard risk patients; OS (P = 0.02) and EFS (P = 0.06), and significantly correlated with poor outcome in non-WNT/non-SHH molecular subgroup; OS (P = 0.0002) and EFS (P = 0.0004)." (PMID 31471537, 2019). "Finally, we showed that significantly increased expression levels of SHH pathway proteins as well as renal CSCs markers were observed in smoker tumor tissues than non-smoker tumor tissues." (PMID 29540668, 2018). "If this is the case, then it is possible that the SHH/GLI pathway may be essential for tumor onset and maintenance, but not for tumor invasion and aggressiveness." (PMID 29137400, 2017). "We demonstrated that OC cell-derived Sonic Hedgehog (SHH) activated Hh signalling in CAFs, which increased the expression of VEGF-C and promoted the capillary tube formation of lymphatic endothelial cells (LECs) in vitro, and induced tumour lymphangiogenesis in vivo." (PMID 28978035, 2017).
tumor (continued). "Furthermore, HIF-1α staining intensity was positively correlated with GLI1 expression, an important component of SHH pathway, in NB tumor samples, which suggests HIF-1α as well as SHH signaling may play an important role in NB initiation or progression." (PMID 25811359, 2015). "However, the interaction between SHH signaling and Wnt signaling in dying tumor cells and its role in tumor cell repopulation had not been elucidated." (PMID 25713298, 2015). "Nevertheless, it is important to underline that our survival analyses were performed within the biologically relevant group of non-WNT/SHH tumours since WNT and SHH tumours have distinctive characteristics and should be analysed separately as independent cohorts." (PMID 25862008, 2015). "Moreover, histological analysis of tumors at the end of the treatment revealed a large central area devoid of proliferating tumor cells specifically in SHH siRNA-treated mice but not in SHH/CDON siRNA-treated animals." (PMID 23940460, 2013). "We also investigated whether SHH pathway blocked by 5E1 or control PBS enhanced chemotherapy efficacy in vivo, the results showed that 10 μg/ml 5E1 treatment led to a significantly greater tumor growth inhibition than those only treated with Oxaliplatin." (PMID 21394208, 2011). "Overall, we showed that the SHH pathway is specifically reactivated in human CRCC and that targeting this pathway might be particularly efficient against this disease, not only through inhibition of tumor growth but also by impeding tumor vascularization." (PMID 20015350, 2009). "This suggests that tumor cells such as C4, C4-2 and C4-2B that are capable of forming tumors and/or metastasizing without stromal support maintain a high level of SHH signaling under adverse growth conditions by maintaining high levels of Perlecan and SHH expression." (PMID 16507112, 2006). "Furthermore, SHH signalling interacts with pathways like Wnt/β-catenin, Notch, and PI3K/Akt/mTOR, suggesting that combination therapies targeting these interactions could synergistically suppress tumour growth." (PMID 39568072, 2024). "However, these analyses primarily focused on immunohistochemical expression and did not investigate whether the SHH pathway was actively driving tumor progression." (PMID 39408773, 2024). "Furthermore, a pilot study testing cetuximab and IPI-926 in patients with recurrent and/or metastatic HNSCC has revealed good tolerability and anti-tumor efficacy, indicating that combinational therapy blocking EGFR and SHH might improve the clinical outcomes for HNSCC patients." (PMID 35048028, 2021). "Importantly, while at the bulk tumor level, all tumors are classified as the SHH tumor subtype based on strong SHH pathway gene expression, CSCs derived from transformed neural stem cells did not depend on SHH signaling for proliferation or survival." (PMID 27608848, 2016). "According to the newly identified pro-apoptotic function of CDON in settings of SHH limitation, we thus investigated whether in SHH-expressing tumors, SHH does not (solely) activate the canonical signaling in stromal cells but also (or rather) blocks CDON-mediated tumor cell death." (PMID 23940460, 2013). "In contrast, NMRAL2P and SHH showed significant negative correlations with multiple immune checkpoint genes, indicating that tumors with higher expression of these genes tend to display a “cold tumor” immune microenvironment, which may correspond to a poorer response to immunotherapy." (PMID 41425595, 2025). "The SHH signaling pathway (including canonical and non-canonical) is involved in different aspects of HCC, including hepatocarcinogenesis, tumor growth, tumor invasiveness, progression, and migration." (PMID 38730691, 2024). "Retrospectively, available tumor tissues were classified into 3 molecular subgroups using immunohistochemistry: 1) WNT, 2) SHH, and 3) non-WNT/non-SHH." (PMID 36649280, 2023).
tumor (continued). "No tumours belong to the WNT subgroup; 51 (17.9%) are SHH, 46 (16.1%) are group 3, and 188 (66.0%) are group 4." (PMID 34667228, 2021). "No studies have compared the expression of SHH in different subtypes of OSCC and focused on the relationship between the tumor parenchyma and stroma." (PMID 31744214, 2019). "The analyses revealed that, despite lack of Sonic HH (SHH) expression, a subset of human cSCC can express GLI1, a marker for active HH signaling, within distinct tumor areas." (PMID 31867038, 2019). "The presence of one or more Hedgehog ligand implies that there is selective pressure on tumor cells to express Hedgehog, but that the exact protein expressed is not critical and that either IHH, SHH, or both will suffice." (PMID 25884700, 2015). "Four GPCRs were also over-expressed to a significant level within all three (WNT, SHH, Non-WNT/SHH) categorized tumor groups (FZD2, RPLP0, EDG4 and F2R)." (PMID 24252460, 2013). "Particularly, Bmi-1, PSP, SHH, OCT4 and Snail were only expressed on CD133 positive cells; none of the five genes were detectable on CD133 negative tumor cells." (PMID 17140455, 2006). "These SHH subtypes were not profoundly visible in the UMAP of bulk data, implying that epigenomic signatures heralding a delayed evolution of SHH-MB tumor may arise from the GNP origin." (PMID 41029754, 2025). "Notwithstanding, the tumor-promoting role of SUFU revealed in our studies does not run contradictory to its status as a tumor suppressor, as the SHH pathway could be activated by way of derepression in MBs with SUFU mutations." (PMID 38358805, 2024). "Although our findings demonstrate that a tumor originating from the vermis is highly predictive (73%) of non-WNT/non-SHH MB, vermian MB may also belong to the WNT-MB or SHH-MB." (PMID 37835571, 2023). "Likewise, loss of IHH, another SHH ligand, by in vivo CRISPR led to more aggressive tumour growth suggesting that IHH, rather than SHH, activates the pathway in stroma to drive its tumour-suppressive effects—a novel role for IHH in the lung." (PMID 36701089, 2023). "Pharmacological activation of SMO receptor using SAG (SMO agonist) increased HHIP-AS1 expression in two independent tumor cell lines, Daoy and CHLA-266, and one primary cell culture, HHU-ATRT1 as well as in non-tumor cells with SHH activation, namely neuronal stem cells (NSC)." (PMID 35831316, 2022). "This embryonal tumor arises in the posterior fossa and can be divided into at least three molecular subgroups: wingless (WNT)-activated MB, Sonic hedgehog (SHH)-activated MB, and non-WNT/non-SHH MB." (PMID 33387268, 2021). "To discover novel drugs with potential anti-tumour activity in human MB, we identified differentially expressed genes common to all non-WNT MB (P < 0.05), namely SHH, Gp3 and Gp4 MB, and mapped expression values to the functionally derived protein interaction network we have described previously." (PMID 34154646, 2021). "In addition, we found that even in the tumor with elevated expression of hedgehog target genes Gli1 and PTCH1, expression of SHH is not necessarily high, suggesting other mechanisms of hedgehog signaling activation in the cancer." (PMID 19943941, 2009). "Interestingly, CPT treatment significantly upregulated SHH, an oncogene that promotes the progression and metastasis in PDAC, but downregulated CCNG2, a key tumor suppressor gene in PDAC, suggesting a pro-tumor activity of Vitamin D in MiaPaca2 cells without epigenetic priming." (PMID 38272889, 2024).
cancer (303 papers, 2006 to 2026). A tumor composed of atypical neoplastic, often pleomorphic cells that invade other tissues. "Within the TME, SHH acts in a paracrine fashion to activate canonical Hedgehog signaling in cancer-associated fibroblasts." (PMID 41550359, 2026). "SHH-activated cancer-associated fibroblasts promote tumor proliferation, invasion, metastasis, and gemcitabine resistance." (PMID 41550359, 2026). "Misregulation of the SHH pathway has been associated with several malignant transformations and plays an essential role maintenaing of cancer stem cells (CSCs), especially those of epithelial origin." (PMID 40952541, 2025). "Accordingly, ablation of SHH in pancreatic tumor cells results in a depletion of cancer-associated fibroblasts, with secondary effects on other stromal cell types." (PMID 37832945, 2024). "In conclusion, the MYCN-associated lncRNA LOXL1-AS1 contributes to SHH-MB metastasis by promoting TGF-β2-mediated cancer stem-like phenotypes." (PMID 38689348, 2024). "Sonic hedgehog (SHH): Dysregulation of the sonic hedgehog (Shh) signaling pathway has been associated with cancer stem cells (CSC) and implicated in the initiation of pancreatic, leukemia, and lung cancers." (PMID 37836558, 2023). "The dysregulated activation of SHH signaling is implicated in several cancers and has been linked to the maintenance of cancer stem-like cells, which are associated with the development of therapeutic resistance." (PMID 33906647, 2021). "Aberrant expression of SHH has been linked to the initiation and progression of numerous cancers, and HH inhibitors targeting SMO are in the clinic against basal cell carcinomas." (PMID 34887403, 2021). "Apart from MB, basal cell carcinoma (BCC) is another cancer with various mutations of SHH pathway components." (PMID 34831357, 2021). "The Sonic Hedgehog (SHH) morphogen pathway is fundamental for embryonic development and stem cell maintenance and is implicated in various cancers." (PMID 34890564, 2021). "Recent studies have shown that the SHH signaling pathway is implicated not only in cancer cells but also in stromal cells." (PMID 33906647, 2021). "We also found that both IGFBP-6 and purmorphamine, a SHH activator, were able to induce mesenchymal stromal cells differentiation with an up-regulation of cancer-associated fibroblasts markers." (PMID 34905501, 2021). "SHH-targeted therapy for OA treatment is consistent with the therapeutic strategy of treating cancers caused by SHH over-activation." (PMID 34646822, 2021). "Dysregulation of the SHH signaling pathway causes the disruption of gastric differentiation, loss of gastric acid secretion, and the development of cancer." (PMID 31979397, 2020). "In other cancers caused by ligand-independent SHH signaling, tumorigenesis can arise from activating SMO mutations or inactivating SUFU mutations." (PMID 32957513, 2020). "Reduced CpG methylation of the SHH promoter has been linked to increased SHH expression in several cancers." (PMID 31027259, 2019). "Multiple cancers have been associated with ligand-dependent activation of Hh signaling by upregulation of SHH or IHH." (PMID 31027259, 2019). "Activation of SHh signaling has been implicated in the tumorigenesis and metastasis of various cancers." (PMID 29416661, 2018). "As Gli TFs constitute the final effectors of the SHh pathway, and are implicated in multiple other oncogenic signaling cascades, they represent an important downstream target for potential cancer therapeutics." (PMID 29416661, 2018). "Use of SHH pathway inhibitor, Vismodegib, in cancer patients is often associated with profound alterations in taste sensation." (PMID 28337150, 2017). "As one of essential signaling cascades characterized well in stem cell differentiation and proliferation, Sonic Hedgehog (SHH) pathway interacts with other cancer-associated signaling molecules like RAS/RAF/MEK/ERK, PI3K/AKT/mTOR, EGFR, and Notch9." (PMID 28507311, 2017).
cancer (continued). "As Gli transcription factors constitute the final effectors of the SHh pathway, and are implicated in multiple other oncogenic signaling pathways, they represent an important downstream target for potential cancer therapeutics." (PMID 27533453, 2016). "GLI transcription factors are the terminal effectors of the SHH pathway and lead to the upregulation of many genes associated with cancer growth and progression." (PMID 27825128, 2016). "Activated SHh has been implicated in tumorigenesis and metastasis in multiple types of cancers including lung, brain, breast, prostate, and skin." (PMID 27533453, 2016). "Re-activation of embryonic SHH signaling, which is essential in normal GI tract organogenesis, can lead to an abnormal healing process associated with oncogenesis, cancer resistance to therapy, and relapse." (PMID 26716648, 2016). "The importance of the SHH pathway for normal development and organ homeostasis is reflected by the fact that mutations in the SHH pathway lead to severe malformations and the development of malignant neoplasms." (PMID 26266257, 2015). "These drugs, such as Cyclopamine, Vismodegib etc. are only effective when a cancer cell with excessive Hedgehog pathway activation, is encountering over-expressed hedgehog ligands (SHH, IHH or DHH) or has mutated PTCH1 or SMO in membrane." (PMID 23935937, 2013). "SHH signaling is important for animal embryonic development and its aberrant activation has been associated with many human cancers." (PMID 22949805, 2012). "Interaction between the MAPK pathway and GLI1 protein of the SHH pathway has been implicated in cancer progression in multiple cancers, and targeting a combination of these pathways could serve as another tool to decipher drug resistance to SHH inhibitors." (PMID 35327484, 2022). "However, aside from cancer, the role of SHH in adult human tissue degeneration and aging-associated degenerative diseases was not well documented." (PMID 34646822, 2021). "Along with the diagnostic potential of detecting NKX6-1 in cancer tissues, our findings suggest that SHH inhibitors could be applied to treat LMS." (PMID 33906647, 2021). "For instance, the hub nodes MYC, NOTCH1 and SHH have been associated to different types of cancer." (PMID 33632303, 2021). "The SHH signaling pathway has been implicated in the progression of cancers." (PMID 33906647, 2021). "Abnormal SHH signaling is not only associated with developmental defects, but also with cancer." (PMID 34203581, 2021). "As Thrb is often silenced or mutated in cancers, it seems that its increase by SHH might actually serve as part of an autoregulatory loop which prevents uncontrollable proliferation of cells." (PMID 32456161, 2020). "However, aberrant SHH pathway activation by either mutation or ligand overexpression is closely correlated with several cancers." (PMID 32957513, 2020). "Though unknown at the time, aberrant SHH signaling was first linked to cancer when Robert J. Gorlin described Gorlin Syndrome (also referred to as naevoid basal cell carcinoma syndrome or basal cell naevus syndrome) in 1960." (PMID 32957513, 2020). "SHH/Gli signaling pathway is significant in carcinomas; following effectors are linked to EMT, and may serve as an potential therapeutic target of many types of cancers." (PMID 31931858, 2020). "However, for most cancers, several types of inhibitors derived from normal stem cell-associated pathways such as SHH, Notch, and TGF-β have been proved to be ineffective in larger studies." (PMID 31186405, 2019). "The role of STIL in promoting SHH signaling could be another pathway to account for its association with cancer." (PMID 29352115, 2018). "All these findings suggest that modulation of SHH by cancer therapy might also be implicated in taste alterations in cancer patients." (PMID 28337150, 2017).